EGFR (epidermal growth factor receptor)
Diseases named in the same sentence as EGFR in open-access papers (continued):
Sharing a sentence is not in itself a finding about the gene and the disease.
head and neck cancer (continued). "Our study focused on relationship between status of uPAR and EGFR pathway in head and neck cancer cells treated by tyrosine-kinase inhibitor gefitinib." (PMID 18519000, 2008). "Therapies that target the EGFR have generated high hopes for the management of head and neck cancer." (PMID 18268492, 2008). "As an example, the antibody used in this study, monoclonal antibody C225, has a high affinity for EGFR and has been shown to be efficacious in several types of cancer, particularly colorectal and head and neck cancers." (PMID 18958173, 2008). "As recently underlined by Forastiere and Burtness (2007), there are compelling clinical data showing that head and neck cancer is an ideal malignancy for EGFR inhibition either with antibodies or small-molecule tyrosine kinase inhibitors." (PMID 18577994, 2008). "For example, the combination of EGFR inhibitors with rapalogues offer a strong potential for further clinical investigations in tumour type responding to EGFR inhibitors such as lung and head-and-neck carcinomas." (PMID 18797463, 2008). "Head and neck cancer is also known to express high levels of EGFR with a strong prognostic value, and the ‘drugable’ relevance of this growth factor has been reported by others and us." (PMID 16940984, 2006). "This is the first study to ever demonstrate a survival benefit related to the administration of an EGFR inhibitor (cetuximab) when combined to RT in head and neck cancer, confirming the promising results provided by previous phase II clinical studies." (PMID 16722544, 2006). "The clearest benefit of EGFR-inhibitor treatment to date is noted when it is combined with RT to treat locally advanced head and neck cancer." (PMID 16722544, 2006). "Although several studies have found overexpression of EGFR and Her-2 in head and neck cancers, the clinical relevance of the finding varies." (PMID 12915878, 2003). "We have previously demonstrated a synergistic interaction between ZD1839 and cisplatin/5-fluorouracil (5FU) in CAL33, a human head and neck cancer cell line that markedly expresses EGFR." (PMID 12888834, 2003). "Recently, targeting of EGFR as a molecular adjuvant therapy has been clinically tried in head and neck cancer." (PMID 12915878, 2003). "Epidermal growth factor receptor appears to be a major prognostic factor in head and neck cancer patients." (PMID 11986789, 2002). "In two head and neck cancer cell lines with comparably elevated epidermal growth factor receptor expression, a two-fold higher ZD1839 IC50 value was found for the one with a constitutively active mitogen-activated protein kinase." (PMID 11986789, 2002). "Elevated levels of epidermal growth factor receptor in head and neck cancer have been extensively reported, and are correlated with poor prognosis." (PMID 11875748, 2002). "Promising clinical results in head and neck cancer have been obtained when EGFR inhibition has been combined with radiotherapy or chemotherapy." (PMID 11875715, 2002). "In addition to the EGFR RTK family, other RTKs like IGF-1R are frequently activated in up to 94% of patient samples and have been implicated in driving head and neck cancer progression." (PMID 40560045, 2025). "Resistance to anti-EGFR therapies in head and neck cancer not only involves overexpression and activation of RTKs but also other factors, such as loss of tumor-suppressor genes, signaling by pattern recognition receptors, and activation of inflammatory pathways." (PMID 40560045, 2025). "However, the mechanism by which IGF-1R crosstalks with EGFR and its impact on head and neck cancer disease progression remains elusive." (PMID 40560045, 2025). "EGFR-targeted therapies (e.g., cetuximab) in head and neck cancers." (PMID 40881676, 2025).
head and neck cancer (continued). "From the clinical studies of the antibody-based agents (i.e., cetuximab-800CW, panitumumab-IRDye800) targeting EGFR in head and neck cancers, a major focus has been on margin assessment in closed-field imaging systems on the back-table or during the pathological processing postoperatively." (PMID 39744227, 2025). "Anti-EGFR therapy has shown promise in specific clinical trials for head and neck cancer." (PMID 40560045, 2025). "Therefore, EGFR was selected as our target moiety, considering its overexpression in up to 90% of head and neck cancers." (PMID 39736115, 2025). "Many head and neck cancers over-express EGFR, resulting in uncontrolled cell proliferation." (PMID 39851804, 2025). "Nimotuzumab, a humanized monoclonal antibody targeting EGFR, has demonstrated good tolerability and may improve radiocurability in unresectable advanced head and neck carcinomas." (PMID 40667483, 2025). "In head and neck cancer, EGFR can be activated through various mechanisms." (PMID 39469621, 2024). "Overexpression of EGFR occurs in solid tumors such as breast, lung, and head and neck cancers." (PMID 38577322, 2024). "Unlike other EGFR ligands, EREG could mimic EGFR mutants by sustaining the activation of the EGFR-Erk pathway in head and neck cancers." (PMID 38250159, 2024). "Co-targeting MPS1 and EGFR could be a promising therapeutic strategy for the treatment of head and neck cancer, particularly OSCC." (PMID 39339232, 2024). "HSC3 cells have been used as a model to study EGFR endocytosis and human head and neck carcinoma." (PMID 38903101, 2024). "Recently, a specific TL for the epidermal growth factor receptor (EGFR) was bound to the surface of 12 nm spherical DNPs by a carbodiimidation reaction to produce nanostructures able to specifically recognize EGFR-positive head and neck cancer cell lines (FaDu and 93-VU)." (PMID 37111590, 2023). "With the help of an anti-EGFR antibody, the nanoparticle could efficiently penetrate head and neck cancer cells and convert near-infrared light into heat to trigger drug release from the PLGA core." (PMID 36902321, 2023). "The in vitro capacity of DFAC, as established in the present study, warrants further investigation in pre-clinical tumor models to establish its performance as a theranostic probe for the treatment of head and neck cancers with potential applicability in other EGFR over-expressing tumor tissues." (PMID 36778405, 2023). "Sapitinib, a ‘quinazoline small’ molecule, showed the most promising results, with EC50 concentrations in the nanomolar range in the four ‘responsive’ lines, which were comparable to those shown in non-small cell lung cancer (NSCLC) and head and neck cancer cell lines designated as EGFR-sensitive." (PMID 36768973, 2023). "High EGFR expression and increased EGFR copy number account for 90% and 21% of cases of head and neck SCC, respectively; however, EGFR mutations are detected in only 1% of head and neck cancer cases." (PMID 37109043, 2023). "A phase 1/2a, open-label, multicenter clinical study using Epidermal growth factor receptor (EGFR)-targeted cetuximab-IR700 in patients with locoregional recurrent head and neck cancer demonstrated good tolerability and clinically meaningful response and survival." (PMID 36297471, 2022). "Previous studies have shown that GNPs coated with poly-allylamine, and functionalized with CTX, selectively target EGFR-overexpressing head and neck cancer cells, have a radiosensitizing effect on these cells in vitro, and in mice show only limited and transient toxicity." (PMID 36324626, 2022). "The prognostic value of HPV infection and EGFR expression in head and neck cancers has been reported as HPV infections on the survival outcomes are identified as a better prognostic factor, and phosphorylated EGFR is associated with longer survival and as a potential therapeutic biomarker." (PMID 36358752, 2022).
head and neck cancer (continued). "The link between toxicity and efficacy was shown in studies evaluating molecular targeted therapies, as the development of rash on monoclonal antibodies targeting the epidermal growth factor receptor resulted in better outcomes in patients with colorectal and head and neck cancer." (PMID 35641203, 2022). "However, despite the latest advancements in cancer diagnostics and therapeutics against EGFR, the survival rates of patients with advanced head and neck cancer remain disappointing due to the resistance to anti-EGFR therapies." (PMID 35052649, 2022). "TLR4 activation has been described to mediate anti-EGFR therapy resistance in head and neck cancer." (PMID 36551979, 2022). "A heterogeneous EGFR expression is also seen in other tumors as head and neck cancer tissues." (PMID 36581931, 2022). "In addition, cSrc activation also contributed to resistance to erlotinib, a small-molecule inhibitor of EGFR, by activating the hepatocyte growth factor receptor in head and neck cancer." (PMID 32989241, 2021). "Hence, therapies targeting EGFR have become more popular for the treatment of head-and-neck cancers." (PMID 34104833, 2021). "Using SPECT/CT the authors were able to demonstrate greater and faster tumor cell uptake of the aptamer-HAuNS conjugate compared to antibody-HAuNS conjugates, suggesting a promising aptamer-based image guided drug delivery mechanism for EGFR positive head and neck cancers." (PMID 34770931, 2021). "Collectively, some head and neck cancer patients might benefit from the combination of cisplatin and an immunotherapy such as EGFR inhibitor." (PMID 34828441, 2021). "Moreover, the addition of bemcentinib has been reported to overcome resistance to EGFR inhibitors in experimental head and neck cancer cell line." (PMID 34877810, 2021). "With the progress that has been made in molecular targeted therapy, anti-EGFR antibody (cetuximab) and immune checkpoint inhibitors (nivolumab, pembrolizumab) have provided survival benefits to head and neck cancer patients and are approved for clinical practice." (PMID 35006440, 2021). "O-glycosylation of EGFR was blocked by C1GALT1 knockdown in head and neck cancer." (PMID 34452648, 2021). "The same group could substantiate the evidence for a radiosensitizing effect of MEHD7945A using human lung and head and neck cancer cells as well as xenografts further supporting the clinical implementation of this EGFR/HER3 combined targeting approach." (PMID 32903756, 2020). "This follow-up provides evidence for the potential of MET CN assessment when patients develop resistance to anti-EGFR therapy and a significant association between the presence of CTCs MET+ and the Overall Survival (OS) in head and neck cancer patients (P = 0.05; HR = 6.66)." (PMID 32102486, 2020). "Agents targeting the epidermal growth factor receptor–mediated (EGFR-mediated) signaling pathway are increasingly used for the treatment of advanced lung, pancreatic, colorectal, and head and neck cancers, which benefit from exacerbated EGFR activity for their growth and survival." (PMID 31805013, 2020). "Gefitinib is an EGFR inhibitor used to treat recurrent head and neck cancers." (PMID 32660019, 2020). "Furthermore, both enzymatically active and inactive HPSE trigger pathways that lead to EGFR phosphorylation, which correlated with head and neck cancer progression." (PMID 33256730, 2020). "These pathways are frequently dysregulated via the overexpression of EGFR in many malignant tumors, including colorectal, lung, and breast cancers, brain tumors, head and neck cancers, pancreatic, kidney, and prostate cancers, and ovarian, bladder, and oral cancers." (PMID 32218834, 2020). "Another example is that mir-7 could influence epidermal growth factor receptor (EGFR) expression and protein kinase B activity in head and neck cancer(HNC)." (PMID 33208088, 2020).
head and neck cancer (continued). "However, all patients with metastatic lung, colorectal, pancreatic or head and neck cancers who initially benefit from EGFR-targeted therapies eventually develop resistance." (PMID 32745124, 2020). "Although a rash induced by other EGFR TKIs (e.g., erlotinib or gefitinib) has been predictive of favorable clinical efficacy in lung, pancreas, and head and neck cancers, it remains unclear if a lapatinib‐induced rash is associated with treatment efficacy." (PMID 33094919, 2020). "Indeed, PFK1 expression and lactate production are under the control of EGFR signaling in CRC cells (this study) as previously observed in head and neck carcinoma cells." (PMID 33025742, 2020). "Partnering with other signaling molecules may also underlie such observed functional heterogeneity, as was shown for the AXL - EGFR (Epidermal Growth Factor receptor), which leads to drug resistance in esophageal and Head and Neck cancers." (PMID 31775787, 2019). "EGFR is an ErbB family member proposed as a therapeutic biomarker in head and neck cancer." (PMID 29419396, 2018). "Among these, the targeted immune-fluorescence imaging is the most promising TFI modality in the field of head and neck cancer surgical navigation due to tissues over-expressing EGFR which can be targeted by FDA-approved EGFR antibodies (e.g., cetuximab, panitumumab)." (PMID 29555901, 2018). "Anti-EGFR molecular therapy shows clinical efficiency in advanced head and neck cancer cases." (PMID 29952994, 2018). "Interfering with this process may increase the efficacy of current T-cell based immunotherapies, not only in head and neck cancer but also in several others types of cancer where overexpression of EGFR is found." (PMID 30192802, 2018). "In head and neck cancer the EGFR is frequently overexpressed." (PMID 29861851, 2018). "Epidermal growth factor receptor (EGFR) nearly expresses in all head and neck carcinoma." (PMID 29952994, 2018). "Antibodies (cetuximab, panitumumab) are approved for use in colorectal and head and neck cancers, whereas small molecule TKIs have been approved for treatment of NSCLC, where response rates are strongly associated with the presence of EGFR-activating mutations." (PMID 27786612, 2017). "Likewise, elevated circulating EGFR-specific CD8+ T cells were found in cetuximab-treated patients with head and neck cancer (HNSCC) as compared with cetuximab-naïve HNSCC patients." (PMID 28674498, 2017). "To test whether the EGFR-GFP localization observed in flank tumor xenografts is common with a physiologically relevant model for head and neck carcinoma, we also performed equivalent experiments using tongue orthotopic xenograft." (PMID 29268862, 2017). "Moreover, AXL overexpression is sufficient to induce resistance to the EGFR inhibitor cetuximab in head and neck cancer cell models." (PMID 27834845, 2016). "The anti-EGFR nanobody D10 has an affinity of 7 nM towards human EGFR and does not compete with the binding site of Cetuximab, the approved anti-EGFR antibody for the treatment of different tumour entities such as colorectal or head and neck cancer (SCCHN)." (PMID 26912069, 2016). "Unlike EGFR in which high expression is associated with poor response to radiation therapy in head and neck cancers, PD-L1 expression has not been found to correlate with treatment outcomes after radiation therapy for head and neck cancers including NPC." (PMID 27341634, 2016). "Furthermore, cetuximab, a chimeric mAb, was FDA approved for the treatment of EGFR-overexpressing metastatic colorectal cancer, metastatic non-small cell lung cancer, and head and neck cancer." (PMID 27891129, 2016). "Our findings reveal a new mechanism by which EGFR/PI3K/Akt/mTOR signaling promotes head and neck cancer progression and underscores the need for developing a therapeutic strategy for targeting IKK/NF-κB either as a single agent or in combination with cisplatin in head and neck cancer." (PMID 26895469, 2016).
head and neck cancer (continued). "Furthermore, Src family kinases has been suggested to increase the EGFR Y845 levels in cetuximab resistant clones derived from lung NCI-H226 cells and also implicated in erlotinib resistance in head and neck cancer." (PMID 27716204, 2016). "The epidermal growth factor receptor (EGFR) is overexpressed in approximately 90% of head and neck squamous cell carcinomas (HNSCC), and molecularly targeted therapy against the EGFR with the monoclonal antibody cetuximab modestly increases overall survival in head and neck cancer patients." (PMID 25946135, 2015). "EGFR-targeted therapy is used in the treatment of head and neck cancer via targeting the pathways involved in tumor growth, angiogenesis, metastasis and invasion, for example, the EGFR inhibitor, gefitinib, has been used in clinical practice in the treatment of head and neck squamous cell carcinoma." (PMID 25997441, 2015). "EGFR is the only targeted therapy approved for the treatment of head and neck cancer." (PMID 25428177, 2014). "However, EGFR inhibition alongside radiation therapy is a proven clinical approach to head and neck cancer." (PMID 25126444, 2014). "However, EGFR-targeted therapy has only modest efficacy in head and neck cancer, through mechanisms that are not fully understood." (PMID 24019973, 2013). "Furthermore, EGFR, a known oncogene in head and neck cancer that is activated by the product of the HPV E5 gene, was strongly expressed in the initial papilloma stage and at all subsequent stages through to SCC." (PMID 23641321, 2013). "In a different model of acquired gefitinib resistance established in the gefitinib-sensitive wild-type EGFR expressing HN11 head and neck cancer cell line, Akt phosphorylation was maintained in the presence of gefitinib, and resistance was overcome by combined EGFR and IGF1R inhibition." (PMID 24339922, 2013). "Ahsan reported that Cbl-dependent EGFR degradation might contribute to sensitivity of head and neck cancer cells to cisplatin." (PMID 24351824, 2013). "Epidermal growth factor receptor (EGFR) is extensively expressed in head and neck cancer." (PMID 24019973, 2013). "SQ20B and FaDu are derived from head and neck cancers with overexpression of EGFR." (PMID 22452803, 2012). "Although EGFR is the most commonly overexpressed tyrosine kinase receptor in head and neck cancer, also other receptors are overexpressed like HER2, HER3, and IL-6 receptor, which could possibly play a role in hypoxia-induced activation of AKT." (PMID 23046567, 2012). "Also, in head and neck cancer patients a strong correlation between EGFR and pEGFR levels has been observed." (PMID 23046567, 2012). "In particular, the expression or activation of EGFR is altered in many epithelial tumours, and both EGFR and ErbB2 are validated targets for cancer chemotherapeutics that are in current use for treatment of breast, lung, colorectal, and head and neck cancers." (PMID 21197469, 2011). "Additionally, we report the first computationally predicted and biologically validated microRNA-regulated network that is dependent on the epidermal growth factor receptor (EGFR) whose overexpression occurs in over 80% of head and neck cancer." (PMID 20369013, 2010). "Targeted therapy in head and neck cancer is closely connected to the use of cetuximab, an anti-Epidermal Growth Factor Receptor (EGFR) antibody therapy, confirmed to be effective in combination with radiotherapy in previously untreated patients in a single controlled clinical trial." (PMID 20482772, 2010). "In chemotherapy refractory head and neck cancers, some are responsive to EGFR target treatment." (PMID 20961443, 2010). "It has been reported that the majority of head and neck cancer, including oral cancer express EGFR." (PMID 20579333, 2010).